TAF1A (TATA-box binding protein associated factor, RNA polymerase I subunit A)
Description:
Component of the transcription factor SL1/TIF-IB complex, which is involved in the assembly of the PIC (pre-initiation complex) during RNA polymerase I-dependent transcription. The rate of PIC formation probably is primarily dependent on the rate of association of SL1/TIF-IB with the rDNA promoter. SL1/TIF-IB is involved in stabilization of nucleolar transcription factor 1/UBTF on rDNA. Formation of SL1/TIF-IB excludes the association of TBP with TFIID subunits.
Synonyms: TAFI48; SL1; MGC:17061; RAFI48
Tractability: Small molecule: it belongs to a druggable protein family. PROTAC: ubiquitination databases record sites on it.
Gene: Protein-coding gene on chromosome 1 (222,557,902 to 222,590,162, reverse strand). Ensembl gene ENSG00000143498.
Subcellular location: Nucleus, nucleolus
Subcellular location (Human Protein Atlas): Microtubules; Nucleoplasm; Basal body; Primary cilium; Primary cilium tip; Primary cilium transition zone
Pathways (Reactome):
Gene expression (Transcription): B-WICH complex positively regulates rRNA expression; NoRC negatively regulates rRNA expression; RNA Polymerase I Promoter Escape; RNA Polymerase I Transcription Initiation; RNA Polymerase I Transcription Termination; SIRT1 negatively regulates rRNA expression
Gene Ontology:
Molecular function: protein binding
Biological process: regulation of DNA-templated transcription; transcription by RNA polymerase I; transcription by RNA polymerase II
Cellular component: RNA polymerase transcription factor SL1 complex; nucleoplasm; nucleolus; RNA polymerase I transcription regulator complex
Genetic constraint (gnomAD): Loss-of-function variants: 34 observed, 56.5 expected, observed/expected ratio (o/e) 0.6, 90% interval 0.46 to 0.8. The upper end of that interval is the gene's LOEUF score, 0.8, which puts it in group 3 of 6, group 1 being the genes least tolerant of losing a copy. Missense variants: 375 observed, 471.04 expected, observed/expected ratio (o/e) 0.8, 90% interval 0.73 to 0.87. Synonymous variants: 158 observed, 161.26 expected, observed/expected ratio (o/e) 0.98, 90% interval 0.86 to 1.12.
Homologues: Orthologues: chimpanzee TAF1A (99% identical), macaque TAF1A (96% identical), rabbit TAF1A (84% identical), dog TAF1A (83% identical), pig TAF1A (82% identical), mouse Taf1a (80% identical), guinea pig TAF1A (78% identical), rat Taf1a (78% identical), tropical clawed frog taf1a (40% identical), zebrafish taf1a (36% identical).
Diseases named in the same sentence as TAF1A in open-access papers:
TAF1A is named in the same sentence as 7 diseases in open-access papers, as found by Europe PMC text mining. Sharing a sentence is not in itself a finding about the gene and the disease. The quoted sentences say what the papers report.
cervical cancer (2 papers, 2021 to 2024). A primary or metastatic malignant neoplasm involving the cervix. "TAF1A, part of the RNA polymerase I complex, is involved in assembling the RNA polymerase I preinitiation complex and has been linked to cell proliferation in cervical cancer, but its role in NB remains unexplored." (PMID 39175876, 2024). "Furthermore, clone formation assays in the HeLa cell line (cervical cancer cell line) revealed that TAF1A and ZBTB41 knockdown significantly inhibits cell proliferation." (PMID 33311601, 2021).
Anxiety (1 paper, 2025). Intense feelings of nervousness, tension, or panic often arise in response to interpersonal stresses. "TAF1A at 1q41 is essential for regulating gene expression, while LINC01502, a long non-coding RNA at 9q34.3, may affect gene expression relevant to intelligence and anxiety." (PMID 40125487, 2025).
cognitive declines (1 paper, 2025). "Conversely, the rs17464857-G allele is associated with a 2.82-unit increase in verbal intelligence scores (p = 6E-6) and is connected to the TAF1A gene, suggesting some genetic factors may mitigate cognitive declines from Caesarean deliveries." (PMID 40125487, 2025).
dilated cardiomyopathy (1 paper, 2021). Cardiomyopathy which is characterized by dilation and contractile dysfunction of the left and right ventricles. "In dilated cardiomyopathy, compound heterozygous recessive mutations in TAF1A exacerbate fibrosis of the explanted hearts." (PMID 33311601, 2021).
tumor (3 papers, 2021 to 2024). "TAF1A (TATA-box binding protein associated factor, RNA polymerase I subunit A) was also a highly up-regulated gene in both cell lines, although it was significantly down-regulated in the tumor (x(T) = −2.12; x(Φ) = 105.70; x(Θ) = 128.88)." (PMID 38790250, 2024). "We examined the transcriptional levels of key tumor-dependent genes (RUVBL1, GTF3C4, TIGD1, and TAF1A) between groups categorized by MYCN expression levels (low vs. high, n = 30 each) using Q-RT-PCR." (PMID 39175876, 2024). "Subsequent experiments showed that the TAF1A and ZBTB41 gene expression in the tumour and normal tissues were significantly different." (PMID 33311601, 2021). "More convincingly, the qRT-PCR clinical tissue samples showed a significant upregulation of TAF1A (P < 0.01) and ZBTB41 (P < 0.05) in tumours compared to the normal healthy tissues." (PMID 33311601, 2021). "In this study, cytological experiments revealed that the TAF1A and ZBTB41 might be involved in the proliferation and migration of tumour cells, and that they may interact endogenously." (PMID 33311601, 2021). "Furthermore, the TAF1A and ZBTB41 were significantly overexpressed in 304 high-grade tumour samples retrieved from the TCGA database (*P < 0.05, **P < 0.01)." (PMID 33311601, 2021). "Additionally, the wound scratch healing assay showed that TAF1A and ZBTB41 knockdown inhibits tumour cell migration." (PMID 33311601, 2021).
cancer (1 paper, 2021). A tumor composed of atypical neoplastic, often pleomorphic cells that invade other tissues. "Besides, ROC curve analysis showed a modest but useful contribution of the TAF1A and ZBTB41 genes to the diagnostic efficiency of the high and low pathological grades of cancer (grade III/IV vs. grade I/II)." (PMID 33311601, 2021).
TAF1A also shares sentences with these, for which no sentence is quoted: Marfan syndrome (1 paper).